KLF13 (KLF transcription factor 13)
Description:
Transcription factor that activates expression from GC-rich minimal promoter regions, including genes in the cells of the erythroid lineage (By similarity). Represses transcription by binding to the BTE site, a GC-rich DNA element, in competition with the activator SP1. It also represses transcription by interacting with the corepressor Sin3A and HDAC1. Activates RANTES and CCL5 expression in T-cells.
Synonyms: RFLAT-1; BTEB3; NSLP1; FKLF-2; FKLF2; RFLAT1
Tractability: PROTAC: ubiquitination databases record sites on it; its protein half-life has been measured.
Gene: Protein-coding gene on chromosome 15 (31,326,706 to 31,435,665, forward strand). Ensembl gene ENSG00000169926.
Subcellular location: Nucleus
Pathways (Reactome):
Developmental Biology: Differentiation of naive CD4+ T cells to T helper 2 cells (Th2 cells)
Gene Ontology:
Molecular function: protein binding; sequence-specific double-stranded DNA binding; DNA-binding transcription factor activity, RNA polymerase II-specific; RNA polymerase II cis-regulatory region sequence-specific DNA binding; DNA binding; DNA-binding transcription activator activity, RNA polymerase II-specific
Biological process: regulation of transcription by RNA polymerase II; transcription by RNA polymerase II; negative regulation of cell population proliferation; negative regulation of erythrocyte differentiation; positive regulation of transcription by RNA polymerase II
Cellular component: nucleus; chromatin
Genetic constraint (gnomAD): Loss-of-function variants: 10 observed, 8.87 expected, observed/expected ratio (o/e) 1.13, 90% interval 0.69 to 1.79. That is too few expected variants to judge how well the gene tolerates losing a copy. Missense variants: 446 observed, 340.19 expected, observed/expected ratio (o/e) 1.31, 90% interval 1.21 to 1.42. Synonymous variants: 245 observed, 164.82 expected, observed/expected ratio (o/e) 1.49, 90% interval 1.34 to 1.65.
Gene-disease validity (ClinGen):
ClinGen rates the evidence that KLF13 causes each of these diseases.
congenital heart disease (autosomal dominant): Moderate. A heart disease that is present at birth.
Homologues: Orthologues: chimpanzee KLF13 (99% identical), macaque KLF13 (98% identical), dog KLF13 (95% identical), pig KLF13 (95% identical), rat Klf13 (94% identical), mouse Klf13 (94% identical), tropical clawed frog klf13 (62% identical), Drosophila melanogaster luna (24% identical), guinea pig Klf13 (17% identical). Paralogues in human: KLF16 (42% identical), KLF14 (40% identical), KLF11 (34% identical), KLF9 (34% identical), KLF10 (31% identical), SP8 (29% identical), SP9 (28% identical), SP7 (28% identical), SP5 (26% identical), KLF12 (25% identical), KLF7 (24% identical), KLF15 (23% identical), and 10 more.
Diseases named in the same sentence as KLF13 in open-access papers:
KLF13 is named in the same sentence as 73 diseases in open-access papers, as found by Europe PMC text mining. Sharing a sentence is not in itself a finding about the gene and the disease. The quoted sentences say what the papers report.
glioma (7 papers, 2020 to 2025). A benign or malignant brain and spinal cord tumor that arises from glial cells (astrocytes, oligodendrocytes, ependymal cells). "For example, KLF13 acts as a tumor suppressor in colorectal cancer, gastric cancer, glioma, pancreatic cancer, and prostate cancer." (PMID 40450000, 2025). "Distinct from CFT, which exerts glioma‐inhibiting effects by regulating KLF13‐mediated epigenetic remodeling, B7 uniquely modulates TIME through GSC‐specific immunostimulatory mechanisms." (PMID 40492418, 2025). "Clofoctol, an antibiotic, is known to upregulate KLF13 gene expression in glioma stem cells and in mouse livers and kidneys." (PMID 38067370, 2023). "Like KLF9, KLF13 was shown to inhibit glioma cell proliferation and invasion in vitro, and moreover, patients with higher tumoral KLF13 expression had a better prognosis than those with lower KLF13 expression." (PMID 38067370, 2023). "Lastly, DNA Methyltransferase I (DNMT1)-mediated hypermethylation of the KLF13 gene promoter with correspondent down-regulation of gene expression in glioma has been reported." (PMID 38067370, 2023). "Interestingly, KLF13 has been identified as a proapoptotic factor that can inhibit cell proliferation and invasion of glioma stem cells." (PMID 37446365, 2023). "Hu et al46 investigated the effect of KLF13 in glioma, and found that the antibiotic clofoctol could suppress the proliferation of glioma stem cells by activating the expression of KLF13." (PMID 32281273, 2020). "Then, through LASSO regression, 5 genes (ADD3, GRHPR, KLF13, RHBDL1 and SLC9A9) closely related to the prognosis of WHO Grade 4 glioma patients were selected." (PMID 37952042, 2023).
colorectal cancer (6 papers, 2020 to 2025). A primary or metastatic malignant neoplasm that affects the colon or rectum. "KLF13 was reported to be upregulated in cervical cancer, but downregulated in colorectal cancer, while reduced KLF13 expression in non-small cell lung cancer tumours indicated poor overall survival." (PMID 40450000, 2025). "This same study demonstrated the potent suppressive effects of KLF13 on the proliferation and colony formation of colorectal cancer cells, on their tumor formation in nude mice, and on tumor cell cholesterol biosynthesis." (PMID 38067370, 2023). "For example, KLF13 suppressed colorectal cancer development via repressing HMGCS1 transcription." (PMID 41410190, 2025). "The literature regarding KLF13 and colorectal cancer is much less robust than that for KLF9." (PMID 38067370, 2023).
hepatocellular carcinoma (5 papers, 2022 to 2026). A malignant tumor that arises from hepatocytes. "On the contrary, KLF13 facilitated hepatocellular carcinoma progression via transcriptional activation of Acyl‐CoA thioesterase 7 to promote fatty acid metabolism." (PMID 41410190, 2025). "Activation of KLF13/ACOT7 axis supports the progression of hepatocellular carcinoma (HCC) through potentiation of oleic acid." (PMID 37003979, 2023).
Obesity (5 papers, 2013 to 2025). Accumulation of substantial excess body fat. "Variations in KLF13 can disrupt the chemokine systems, which are closely linked to energy metabolism, insulin resistance, and obesity." (PMID 39202416, 2024). "Recent studies identified a site of CpG methylation within the KLF13 gene that was significantly associated with body mass index, obesity, and appetite regulation." (PMID 38067370, 2023). "We also found two cis-meQTL SNPs (rs11537749 and rs12595641) of KLF13 associated with obesity-related cg07814318 methylation." (PMID 28508896, 2017). "The association found in the literature between KLF13 methylation and orexigenic features, as well as digestive physiology and obesity, may be attributed to inflammatory conditions resulting from altered KLF13 activity." (PMID 39202416, 2024). "Since adipogenesis underlies obesity and consequent adipocytokine secretion, and several adipocytokines are cancer-promoting (e.g., leptin), KLF9 and KLF13 may significantly affect cancer pre-disposition indirectly through their targeted actions on fat depots." (PMID 38067370, 2023). "This differential cg07814318 methylation of KLF13 with pre-adipocytes related to obesity may imply its early epigenetic role in differentiation or proliferation of pre-adipocytes." (PMID 28508896, 2017). "Differential DNA methylation patterns in the KLF13 gene of blood samples showed that this criterion could be used as a surrogate for representing epigenetic changes in cells related to obesity." (PMID 28508896, 2017). "The sequencing variations within KLF13 genes could drive dynamic modifications of obesity-related CpG methylation." (PMID 28508896, 2017). "Our data suggest the genetic context of the KLF13 locus could drive epigenetic modification of the obesity-related DMPs in extreme high-BMI children." (PMID 28508896, 2017). "The epigenetic perturbation of KLF13 may affect glucose tolerance and obesity separately." (PMID 28508896, 2017). "Differential DNA methylation patterns in the KLF13 gene determined from separate blood samples showed that this criterion could be used as a surrogate for representing overall epigenetic changes in cells related to obesity." (PMID 28508896, 2017).
lupus (4 papers, 2020 to 2025). "Thus, miR-125a may play a part in lupus CD4+T cells by targeting the 3′-UTR of KLF13." (PMID 33750387, 2021).
cervical cancer (3 papers, 2023 to 2025). A primary or metastatic malignant neoplasm involving the cervix. "In contrast, KLF13 is over-expressed in cervical cancer cell lines, and KLF13 expression in normal cervical epithelium is low but increases in intraepithelial cervical neoplasia and invasive squamous cervical cancer." (PMID 38067370, 2023). "The transcription factor KLF13 (Krüppel-like factor 13) is vital for ATM activity and for STAT5 activation, and some studies showed that pSTAT5 plays a major role in cervical cancer pathogenesis." (PMID 38999946, 2024).
congenital heart disease (3 papers, 2020 to 2025). "Deletion of KLF-13 (as well as other GATA4 modifier factors) has been associated with congenital heart defects, including Holt–Oram syndrome (discussed in a subsequent section), atrial and septal malformations, and ventricular hypotrabeculation." (PMID 36836777, 2023). "Other variations in KLF-13 have been linked to congenital heart defects, such as the Glu144*-mutant of KLF13, which cannot trans-activate VEGF-a and ANP gene promoters, which is associated with patent ductus arteriosus, ventricular septal defect, and bicuspid aortic valve." (PMID 36836777, 2023). "This study suggested that CHD patients harbored KLF13 gene variants, and KLF13 variants may contribute to the occurrence of congenital heart disease." (PMID 32293321, 2020). "Previously, we showed that KLF13 is a TBX5 cofactor and that KLF13 may be a genetic modifier of Holt-Oram Syndrome and possibly other congenital heart diseases." (PMID 32293321, 2020).
gastric cancer (3 papers, 2022 to 2025). A primary or metastatic malignant neoplasm involving the stomach. "On the contrary, autophagy inhibitor CQ was found to reverse down-regulation of β-catenin expression caused by KLF13 overexpression in gastric cancer cells." (PMID 36336731, 2022). "In this paper, we investigated the effect of KLF13 on gastric cancer proliferation and explored underlying mechanism." (PMID 36336731, 2022). "Here, we aimed to investigate the role of KLF13 in gastric cancer and explored underlying molecular mechanisms." (PMID 36336731, 2022). "KLF13 overexpression turned out to induce cell arrest at G2/M phase in both gastric cancer cell lines." (PMID 36336731, 2022). "As a result, KLF13 inhibited gastric cancer proliferation by triggering the autophagic degradation of β-catenin and reduced expressions of Cyclin D1 and c-Myc." (PMID 36336731, 2022). "Collectively, our results firstly demonstrate the role of KLF13 in gastric cancer proliferation and provide a further understanding of the molecular mechanism underlying this process." (PMID 36336731, 2022). "Then, Kaplan–Meier Plotter website was employed to analyze correlation of KLF13 expression with prognosis of gastric cancer." (PMID 36336731, 2022). "Firstly, it was found that KLF13 expression was significantly decreased in gastric cancer tissues and cancer cells compared with adjacent normal tissues and normal gastric epithelial cells, respectively." (PMID 36336731, 2022). "To elucidate the effect of KLF13 on gastric cancer growth in vivo, we constructed a xenograft tumor model using female BALB/c nude mice with stable-transfection cell lines of BGC-823 and SGC-7901." (PMID 36336731, 2022). "Our results showed that KLF13 overexpression obviously inhibited tumor growth of gastric cancer compared to the corresponding control group in both cell lines." (PMID 36336731, 2022). "Taken together, KLF13 also restrained gastric cancer proliferation through decreasing β-catenin expression in vivo." (PMID 36336731, 2022). "In vivo, KLF13 overexpression also suppressed xenograft tumor growth of gastric cancer and down-regulated expressions of Ki67, β-catenin, Cyclin D1, and c-Myc in tumor tissues." (PMID 36336731, 2022). "All these data further demonstrated that KLF13 suppressed cell proliferation through promoting β-catenin degradation in autophagy-dependent manner in gastric cancer in vitro." (PMID 36336731, 2022). "In this paper, we found that KLF13 overexpression inhibited gastric cancer proliferation both in vitro and in vivo." (PMID 36336731, 2022). "Firstly, we collected 29 pairs of tumor tissues and adjacent normal tissues, and immunohistochemistry assay was conducted to reveal the expression pattern of KLF13 in gastric cancer." (PMID 36336731, 2022). "Meanwhile, we also detected KLF13 expression in normal gastric epithelial cells and gastric cancer cells." (PMID 36336731, 2022). "KLF13 up-regulation facilitated co-localization and binding of β-catenin with autophagy protein p62, and exogenous overexpression of β-catenin or blocking autophagy process appeared to reverse KLF13-induced inhibition of gastric cancer proliferation." (PMID 36336731, 2022). "Based on these results, we speculated that β-catenin-dependent CCND1 and MYC transcriptions appeared to be involved in KLF13-induced suppression of gastric cancer proliferation." (PMID 36336731, 2022). "As a result, KLF13 expression level positively contributed to a better prognosis of gastric cancer." (PMID 36336731, 2022). "Collectively, these results reminded us that KLF13 might affect cell proliferation and cell cycle in gastric cancer." (PMID 36336731, 2022). "Collectively, these data firstly demonstrated the involvement of KLF13 in inhibiting cell proliferation of gastric cancer through promoting autophagy-dependent degradation of β-catenin, which reinforced the evidence for suppressive roles of KLF13 in human tumors." (PMID 36336731, 2022).
gastric cancer (continued). "To further demonstrate this speculation, we exogenically overexpressed β-catenin in gastric cancer cells transfected with KLF13 plasmid and analyzed expressions of CCDN1 and MYC, along with viability of cell proliferation." (PMID 36336731, 2022). "Taken together, these data revealed that KLF13 played a suppressive role in gastric cancer and its overexpression could inhibit cell proliferation and induce cell arrest at G2/M phase." (PMID 36336731, 2022). "Then, our results further demonstrated that KLF13 could obviously inhibit gastric cancer proliferation and induce cell arrest at G2/M phase." (PMID 36336731, 2022). "Collectively, our results suggested that KLF13 expression was inhibited with the tumorigenesis of gastric cancer, and it might function as a suppressive factor in gastric cancer." (PMID 36336731, 2022). "However, KLF13 expression in gastric cancer tissues was quite weak or even lost." (PMID 36336731, 2022). "Nevertheless, the roles that KLF13 plays in gastric cancer remain unclear." (PMID 36336731, 2022). "Consequently, we investigated whether KLF13 could affect β-catenin to inhibit cell proliferation in gastric cancer." (PMID 36336731, 2022). "Moreover, KLF13 was demonstrated to induce cell arrest at G2/M phase in gastric cancer cells, and thus we also analyzed whether CQ could reverse this effect." (PMID 36336731, 2022). "Moreover, we firstly found that KLF13 overexpression could suppress gastric cancer proliferation both in vitro and in vivo." (PMID 36336731, 2022). "However, β-catenin expression at protein level was obviously reduced in gastric cancer cells transfected with KLF13 plasmid, which revealed that KLF13 might regulate β-catenin expression via translation or post-translation process instead of transcription level." (PMID 36336731, 2022). "Zinc protein KLF13 is a tumor-suppressive member of Kruppel-like factors family, and yet the effect of KLF13 on gastric cancer has not been reported." (PMID 36336731, 2022). "Moreover, analyses of Western blot and RT-qPCR suggested that β-catenin overexpression was able to rescue KLF13-mediated down-regulation of CCND1 and MYC expressions in both gastric cancer cell lines." (PMID 36336731, 2022). "KLF13 overexpression could reduce p62 expression and promote the specific expression of LC3-II subtype in both two cell lines, which suggested that KLF13 triggered the autophagy flux in gastric cancer cells." (PMID 36336731, 2022).
pancreatic cancer (3 papers, 2023 to 2025). "KLF13 was confirmed to inhibit the EMT process of pancreatic cancer by promoting the transcription of LINC00261 and suppressing the expression of metastasis-associated proteins, thus, inhibiting the metastasis of pancreatic cancer." (PMID 37239940, 2023). "Thus, the sequence of events during pancreatic cancer tumorigenesis is upregulation of KLF13, resulting in increased levels of LINC00261 and a decrease in PI3K/AKT/mTOR pathway activity, leading to a decline in metastasis." (PMID 37239940, 2023).
prostate carcinoma (3 papers, 2022 to 2025). A carcinoma that arises from epithelial cells of the prostate gland. "KLF9 and KLF13 both regulate the differentiation and proliferation of fat cells internally and can serve as potential therapeutic targets for prostate cancer cell proliferation." (PMID 39272379, 2024). "KLF13 expression was inhibited in prostate cancer while its overexpression could restrain cell proliferation of prostate cancer through depressing AKT activation." (PMID 36336731, 2022). "Both KLF9 and KLF13 inhibit the activation of the AKT signaling pathway, thereby suppressing the growth of prostate cancer cells." (PMID 39272379, 2024).
atrial fibrillation (2 papers, 2025 to 2026). A disorder characterized by an electrocardiographic finding of a supraventricular arrhythmia characterized by the replacement of consistent P waves by rapid oscillations or fibrillatory waves that vary in size, shape and timing and are accompanied by an irregular ventricular response. "The outcomes propose that miR-107-3p may modulate atrial fibrillation by regulating KLF13 expression." (PMID 41278196, 2025).
colon cancer (2 papers, 2023 to 2024). "Integrated analysis demonstrated that KLF13 may be involved in tumorigenesis and metastasis in colon cancer." (PMID 39273015, 2024).
diabetes (2 papers, 2017 to 2024). "Skeletal muscle‐specific KLF13 overexpression also markedly alleviated diabetes‐associated muscle loss and improved the strength of diabetic mice." (PMID 38973459, 2024). "Next, KLF13 or control adeno‐associated virus 9 (AAV9) vectors were injected in situ into the Gas of diabetic mice (STZ + HFD; spontaneous diabetes mouse model) to evaluate the effects of KLF13 overexpression on muscle atrophy." (PMID 38973459, 2024). "The analysis of publicly available transcriptomics data (dataset GEO: GSE156249) further demonstrates that KLF13 expression is downregulated in skeletal muscle from patients with diabetes compared with healthy controls." (PMID 38973459, 2024). "KLF13 overexpression preserved muscle mass (Gas: 100 ± 6.38 vs. 120 ± 14.4, P < 0.01) and the exhaustive running distance (423.8 ± 59.04 vs. 530.2 ± 77.45, P < 0.05) in an in vivo diabetes‐induced skeletal muscle atrophy model." (PMID 38973459, 2024).